THPO (thrombopoietin)
Diseases named in the same sentence as THPO in open-access papers (continued):
Sharing a sentence is not in itself a finding about the gene and the disease.
Thrombocytopenia (continued). "The clinical pharmacist attributed the thrombocytopenia to voriconazole exacerbating the hematological toxicity of selpercatinib and thus stopped selpercatinib and voriconazole treatment sequentially; the patient was given recombinant human thrombopoietin to raise platelets." (PMID 41939461, 2026). "In addition, the degree of hepatic dysfunction associated with a thrombopoietin synthetic defect needs to be elucidated alongside the detailed pathways, as some studies challenge the notion that TPO itself is the main cause of thrombocytopenia in chronic liver disease." (PMID 40095848, 2025). "The genesis of thrombocytopenia in cirrhosis is multifactorial, as demonstrated by the normal reticulated platelets: accelerated removal of platelets from the circulation with high turnover and reduced bone marrow production because of reduced hepatic production of thrombopoietin." (PMID 40719417, 2025). "Moreover, thrombocytopenia may directly result from liver injury due to the impairment of thrombopoietin production." (PMID 40550831, 2025). "In the case of normal values of platelet lifespan, dysfunction of B-lymphocytes, cytostatic T-lymphocytes, autoantibodies’ influence on megakaryocytes, and partial or complete absence of thrombopoietin may cause weak platelet production and thrombocytopenia." (PMID 40722539, 2025). "In fact, thrombocytopenia is a common complication of CLDs due to splenic platelets’ sequestration, immune-mediated peripheral destruction, bone marrow suppression caused by HCV infection and its treatment, or by a decreased concentration of hematopoietic growth-factor thrombopoietin." (PMID 39201990, 2024). "Furthermore, hepatocytes are also key producers of the platelet regulator thrombopoietin, thus, hepatocellular dysfunction may impair platelet production and exacerbate thrombocytopenia." (PMID 37223472, 2023). "Moreover, an imbalance in the bone marrow microenvironment may impair thrombopoietin production as well as megakaryocyte differentiation and maturation to some extent, thereby contributing to thrombocytopenia." (PMID 37841241, 2023). "In recent years, clinical studies have illustrated that recombinant human thrombopoietin (rhTPO) can significantly stimulate platelet production and increase peripheral platelet counts, which is primarily used to manage chemotherapy-induced thrombocytopenia and primary immume thrombocytopenia (ITP)." (PMID 36299903, 2022). "Thrombin generation can be normal in the plasma of individuals with cirrhosis, and that might justify platelet transfusion or treatment with recombinant human thrombopoietin in those patients with severe thrombocytopenia when they bleed spontaneously or before undergoing surgery or liver biopsy." (PMID 34066706, 2021). "Our previous study demonstrated that administration of recombinant human thrombopoietin (rhTPO) with conventional medical therapies could significantly improve the PCs in severe sepsis patients with thrombocytopenia and effectively reduce the platelet transfusion possibility." (PMID 25986785, 2015). "Bone marrow involvement by lymphoma led to megakaryocyte dysfunction, while liver involvement resulted in reduced thrombopoietin (TPO) production, both contributing to severe thrombocytopenia." (PMID 40696688, 2025). "Reduced production of thrombopoietin (TPO) and, to a lesser extent, erythropoietin (EPO), also plays a role in the development of thrombocytopenia and anemia, respectively." (PMID 40095848, 2025). "(a) Schematic diagram of thrombopoietin (TPO) (3000 U/kg) and VLZ (2.5, 5, and 10 mg/kg) administration in Kunming (KM) mice with thrombocytopenia induced by IR." (PMID 38573820, 2024). "The etiology of thrombocytopenia in CKD patients is not fully understood; however, the possible mechanisms include reduced production of thrombopoietin, accelerated platelet destruction, and impaired platelet formation." (PMID 39219970, 2024).
Thrombocytopenia (continued). "There was a trend towards higher rates of grade 4 thrombocytopenia in the prior BCMA-TT cohort (46% versus 32%; p = 0.064), which translated to a higher rate of thrombopoietin mimetic use (27% versus 12%; p = 0.013) for the prior BCMA-TT group." (PMID 37558706, 2023). "We first show the JMJD1C expression difference in the PMA-induced cell line models, the thrombopoietin (TPO)-induced megakaryocyte differentiation of the cord blood cells, and also the thrombocytopenia patients, compared to the normal controls." (PMID 36429088, 2022). "Subsequently, it was decided by the treating physician to try off-label treatment with the thrombopoietin (TPO) receptor agonist eltrombopag, since it has recently been reported to increase platelet counts in different forms of inherited thrombocytopenias." (PMID 34858435, 2021). "Genetic alterations of the thrombopoietin (TPO)/MPL/JAK2 axis leading to thrombocytosis and thrombocytopenia." (PMID 28955303, 2017). "At present, the suggestion is that hypersplenism, decreased thrombopoietin (TPO) synthesis and bone suppression result in thrombocytopenia in patients with liver cirrhosis." (PMID 24137205, 2013). "Since platelet apoptosis stimulates the thrombopoietin pathway, others have suggested that ramp-up dosing of BCL-XL inhibitors may help stimulate endogenous TPO production and avoid severe thrombocytopenia that can be life threatening." (PMID 41507122, 2026). "In addition, thrombocytopenia (low PLT counts) is common in liver disease, and the possible mechanisms include hypersplenism in cirrhosis, reduced thrombopoietin production by the liver, or immunological removal of platelets from the circulation." (PMID 41424785, 2025). "A prospective study conducted at a single center demonstrated that in non-small for gestational age (non-SGA) infants with thrombocytopenia, thrombopoietin levels are elevated to enhance platelet production." (PMID 40822693, 2025). "Thrombocytopenia, also known as low platelet count, is common in chronic liver disease due to a lack of sufficient thrombopoietin in normal liver tissue and/or increased platelet destruction due to splenomegaly." (PMID 39834808, 2024). "Despite the promising safety profiles and potential efficacy observed with recombinant thrombopoietin agonists (rhTpo) such as romiplostim, as well as second-generation TpoRas like eltrombopag in treating post-HSCT thrombocytopenia, the existing studies have several notable limitations." (PMID 39290805, 2024). "Compared to the non-EMD group, there was a higher incidence of any grade (95% vs 74%, p = 0.0006) and grade ≥3 thrombocytopenia (62% vs 38%, p = 0.0087) in the EMD group which translated to a higher rate of thrombopoietin agonist use (38% vs 15%; p = 0.02) for the EMD group." (PMID 38821914, 2024). "Mutation of the THPO gene is known to cause congenital amegakaryocytic thrombocytopenia (CAMT2), which is a rare inherited disorder characterized by early infancy thrombocytopenia and absent or decreased megakaryocytes with gradual progression to pancytopenia." (PMID 39479124, 2024). "Plasma thrombopoietin (TPO) measurements help distinguish between different types of thrombocytopenia but are not feasible in routine clinical practice." (PMID 35204403, 2022). "The increased incidence of thrombocytopenia in VLBW newborns may be due to a partial response to thrombocytopenia in terms of platelet and thrombopoietin production, mostly during sepsis with diminished energy reserves in the host." (PMID 35386168, 2022). "Thrombocytopenia in patients with chronic HCV is multifactorial; HCV promotes hepatic necroinflammation and fibrosis resulting in impaired liver function and decreased production and activity of thrombopoietin." (PMID 34122539, 2021). "Adult mice lacking the MPL or THPO gene, appear normal except for thrombocytopenia but have a marked increase in plasma THPO and a decrease in marrow HSC." (PMID 32479500, 2020).
Thrombocytopenia (continued). "Twenty-nine of 35 patients with ITP in pregnancy had thrombopoietin values >500 pg/mL, whereas none of the gestational thrombocytopenia patients' thrombopoietin levels exceeded 500 pg/mL." (PMID 26840092, 2016). "Thrombopoietin has no contribution for the occurrence of thrombocytopenia in cirrhosis; splenic sequestration seems to be the main factor." (PMID 24976834, 2014). "To analyze whether the thrombocytopenia observed in AHF patients could be the result of altered megakaryopoiesis, we used an in vitro model of human CD34+ cells stimulated with thrombopoietin (TPO)." (PMID 20419155, 2010). "After the cessation of clinical trials of first generation thrombocytopenic growth factors due to immunogenicity issues, the introduction of non-immunogenic second-generation thrombopoietin mimetics has opened a novel way to treat thrombocytopenia." (PMID 21415945, 2010). "Finally, the identification, cloning and characterization of thrombopoietin as the primary regulator of platelet production, as well as a critical effector of HSC biology, have led to its clinical development for patients with thrombocytopenia of several origins, as well as aplastic anemia." (PMID 38672505, 2024). "Based on the reported case, we highly recommend performing genetic testing in case of thrombocytopenia and absent or decreased megakaryocytes, as CAMT2 is mild and can respond to THPO receptor agonists while avoiding invasive, ineffective bone marrow transplantation for these THPO gene mutations." (PMID 39479124, 2024). "Serum thrombopoietin concentration was determined in ITP in pregnancy (n = 35), gestational thrombocytopenia (n = 31), healthy pregnancy (n = 32), age-matched nonpregnant ITP (n = 32) and nonpregnant healthy controls (n = 35) by ELISA." (PMID 26840092, 2016). "Eltrombopag is a non-peptide, small molecule thrombopoietin (TPO) receptor agonist that promotes megakaryopoiesis similar to endogenous human TPO and may be an effective agent for thrombocytopenia in this patient population." (PMID 25886818, 2015).
Thrombocytosis (69 papers, 2008 to 2025). Increased numbers of platelets in the peripheral blood. "The observed marked thrombocytosis was likely associated with an inflammatory response, as increased thrombopoietin is a component of the acute-phase reaction." (PMID 40343115, 2025). "The production of hepatic thrombopoietin and subsequent thrombocytosis is caused by elevated levels of thrombopoietin-inducing cytokines, such as interleukin-1 (IL-1), IL-3, IL-11, and tumor-derived IL-6, in tumor-host tissues." (PMID 39941717, 2025). "Thrombocytosis occurring in HCC is an uncommon paraneoplastic phenomenon linked to the release of thrombopoietin (TPO) or the megakaryocyte growth factor from both hepatocytes and bone marrow cells." (PMID 38674198, 2024). "Previous research has found that tumor cells cause thrombocytosis by boosting hepatic thrombopoietin (TPO) expression via IL-6 activation." (PMID 36531011, 2022). "Hereditary THPO mutations causing uncontrolled THPO synthesis are associated with isolated thrombocytosis." (PMID 33777803, 2021). "Still, in the present classification of pediatric thrombocytosis, germline mutations known to cause elevated THPO levels were grouped among the forms of primary thrombocytosis." (PMID 33712866, 2021). "In ovarian cancer, thrombocytosis is linked to elevated tumor interleukin-6 and liver-generated thrombopoietin and is associated with shortened overall survival of patients." (PMID 34367949, 2021). "Among the causes of thrombocytosis is the capability of some tumor cells to produce thrombopoietin, and an upregulation of the platelet activation markers, such as P-selectin, β-thrombomodulin, or CD40 ligand, contributing to an increase in the platelet count." (PMID 35008814, 2021). "Hereditary THPO mutations permitting unregulated THPO production caused thrombocytosis alone, but in one family were associated with leukemic transformation or myelofibrosis." (PMID 32479500, 2020). "The molecular basis of hereditary thrombocytosis is germline mutations affecting the thrombopoietin (TPO)/TPO receptor (MPL)/JAK2 signaling axis." (PMID 28979237, 2017). "When uORFs are somehow eliminated from the thrombopoietin mRNA, the translation of thrombopoietin gene is increased and thus the amount of the platelets, causing thrombocythaemia." (PMID 20042076, 2009). "Acute bacterial, viral, or chronic infections (e.g., tuberculosis) may cause secondary thrombocytosis by increasing thrombopoietin synthesis through increased inflammatory component IL-6." (PMID 40528397, 2025). "In carcinoma‐associated thrombocytosis, it is hypothesized that tumor production of IL‐6 directly leads to the generation of hepatic thrombopoietin (TPO), which stimulates megakaryocytic generation of platelets." (PMID 34881459, 2022). "Carcinoma‐associated thrombocytosis involves tumor production of mediators such as interleukin‐6 (IL‐6) and thrombopoietin (TPO) that increase thrombopoiesis and may play a role in tumor evasion and metastasis." (PMID 34881459, 2022). "Moreover, transient myeloproliferative disease was reported in two infants of a family affected by hereditary thrombocytosis caused by a mutation in intron 3 of the THPO mRNA." (PMID 33712866, 2021). "Moreover, hepatic IL-6 induces the synthesis of hepcidin, ultimately causing functional iron deficiency, chronic inflammation-associated anemia, and thrombopoietin, which induces thrombocytosis, as specifically demonstrated in ovarian cancer." (PMID 33550983, 2021). "Primary hereditary thrombocytosis may be caused by germline mutations within the genes encoding key regulators of thrombopoiesis, i.e., thrombopoietin (THPO) and its receptor c-MPL (MPL) or the receptor’s effector kinase Januskinase2 (JAK2)." (PMID 33712866, 2021). "Germline GOF mutations in the THPO gene have been described in hereditary thrombocytosis." (PMID 28955303, 2017).
Thrombocytosis (continued). "Of interest in this respect is the notion that the amino acid sequence homology of thrombopoietin and erythropoietin might explain thrombocytosis in children with iron-deficiency anemia." (PMID 18380894, 2008). "The cause of tumor-associated thrombocytosis remains unclear, however, the tumor-associated production of granulocyte-macrophage colony-stimulating factor or thrombopoietin (TPO) mediated by interleukin-6 is considered to be responsible for the increase in PLT count observed in cancer patients." (PMID 25663931, 2015). "In secondary thrombocytosis, inflammatory compounds (e.g., IL-6) increase thrombopoietin secretion and subsequent megakaryocyte production, increasing platelet count." (PMID 40528397, 2025). "In a mouse model, hepatic thrombopoietin synthesis is upregulated in response to tumor-derived IL-6 by the mechanism of paraneoplastic thrombocytosis." (PMID 39941717, 2025). "Regarding the mechanism underlying this relationship, in response to the overproduction of tumor-derived IL-6, the hepatic synthesis of thrombopoietin increases, inducing secondary thrombocytosis." (PMID 39762819, 2025). "IL-6, as a key upstream regulator of JAK/STAT signaling, can activate STAT3 and related downstream molecules, enhance thrombopoietin expression, and drive excessive myeloid proliferation, ultimately leading to secondary (reactive) thrombocytosis." (PMID 41438978, 2025). "Circulating TPO concentrations have been shown to correlate with C-reactive protein levels, further supporting the link between systemic inflammation and thrombopoietin-driven thrombocytosis." (PMID 41552126, 2025). "In ovarian cancer mouse models, silencing of thrombopoietin and IL-6 reduced levels of thrombocytosis, suggesting that thrombopoietin and IL-6 are the major drivers of thrombocytosis in ovarian cancer." (PMID 39518024, 2024). "The possible mechanism of MPM-related thrombocytosis is that mesothelioma cells persistently secrete interleukin-6, which stimulate thrombopoietin to induce thrombocytosis." (PMID 38267958, 2024). "ThPO overexpression in HSPCs first leads to leukocytosis and thrombocytosis and, over time, with onset of fibrosis, reduced hemoglobin and erythrocyte counts." (PMID 39155965, 2024). "Thrombocytosis is explained by the paraneoplastic phenomenon that arises from tumor secretion of the proinflammatory cytokine interleukin-6, which increases thrombopoietin." (PMID 36626395, 2023). "Xu and colleagues observed that anti-GPIba antibodies decrease thrombopoietin generation and inhibit tumor-induced thrombocytosis." (PMID 36901997, 2023). "Paraneoplastic thrombocytosis in ovarian cancer is due to IL-6 originating from cancer cells and consequent thrombopoietin released from the liver." (PMID 36831623, 2023). "Thrombopoietin has been reported to induce thrombocytosis and thrombosis in a mouse study, with platelets playing a vital role in thrombosis by interacting with cancer cells to promote their activation and aggregation." (PMID 37143160, 2023). "In turn, tumor cells can promote thrombocytosis by secreting thrombopoietin, which is correlated with poorer outcome in solid cancers such as pancreatic adenocarcinoma and non-small cell lung cancer." (PMID 36766755, 2023). "IL-6 was increased in DS-TB patients, and evidence suggests that this cytokine promotes thrombocytosis and regulates thrombopoietin levels." (PMID 36325331, 2022). "For example, interleukin-6 (IL-6) released from ovarian cancer cells can stimulate the secretion of thrombopoietin in the liver and it eventually leads to thrombocytosis." (PMID 36158646, 2022). "IL-6 subsequently binds to its receptor (IL6R) on hepatocytes to enhance the production of thrombopoietin, thereby regulating platelet production and resulting in diabetes-induced thrombocytosis." (PMID 35330392, 2022).